AKT1 (AKT serine/threonine kinase 1)
Diseases named in the same sentence as AKT1 in open-access papers (continued):
Sharing a sentence is not in itself a finding about the gene and the disease.
cancer (continued). "Our prediction results suggest that AKT1 has a high degree in this pathway, and the phosphorylated form is a biomarker for cancer and tumor biology." (PMID 33912040, 2021). "As evidenced by the behavior of loss-of-function mutants of PTEN in the context of a gain-of-function mutation of AKT1, the PTEN-AKT1 signaling pathway plays a critical role in human cancers." (PMID 33568640, 2021). "Suppression of STBD1—either via knockdown or expression of the mutant—also promotes the expression of multiple cancer hallmark genes, including c-Myc, NFKB1, and AKT1, although the exact underlying mechanisms remain to be determined." (PMID 34059679, 2021). "AKT1 activation can induce PI3K/AKT pathway activation, which is one of the most frequently activated pathways in cancer." (PMID 33738258, 2021). "The common TMPRSS2 and FURIN associated genes CTSL, MYC, AKT1, and SRC displayed positive correlations with their corresponding subjects except for the FURIN and MYC correlation in cancers (R 0.012; p 0.199)." (PMID 33796097, 2021). "In PCa, genetic changes (e.g., activation mutation or deletion of PIK3CA, Akt1 and PTEN, epigenetic and post-translational modifications) leads to dysregulation of PI3K pathway and hence regulates cancer progression, including PCa." (PMID 33848262, 2021). "Subsequently, we selected an enriched pathway (hsa05200: pathways in cancer) and intersected with the top 10 hub genes, and we showed that there are 4 overlapping genes (AKT1, MAPK8, AR, and MDM2)." (PMID 33511213, 2021). "Whereas Akt2 promotes growth factors-induced epithelial–mesenchymal transition (EMT), a process that promotes cancer metastasis, Akt1 negatively regulates EMT." (PMID 34419139, 2021). "In cancer cells, AKT1 is involved in proliferation and growth, promoting tumor initiation and suppressing apoptosis, whereas AKT2 regulates cytoskeleton dynamics, favoring invasiveness and metastatization." (PMID 33995085, 2021). "AKT1, AKT2, and AKT3 were reported in very few cases of TC and some AKT1 mutations were reported in ATC and in FTC and in a TC metastasis, suggesting that this mutation can occur late during cancer progression." (PMID 33803747, 2021). "Opposing roles of Akt1 and Akt2 in cell cycle progression, migration and invasion have been detected in various types of human cancer." (PMID 34419139, 2021). "AKT1 is the core member of the proliferation and survival pathway most frequently activated in cancers." (PMID 33692692, 2021). "More importantly, the IGF-1/IGF-1R system mediates stimulatory effects in cancer cells via different routes such as the phosphatidylinositol-3kinasw(PI3K)/Akt1, mTOR, and MAPK." (PMID 35010954, 2021). "Oct4 maintained the cancer cell survival partly by inhibiting apoptosis through the Oct4/TCL1/AKT1 pathway where Tcl1 enhances the kinases activity of Akt1 to promote cell proliferation." (PMID 34613998, 2021). "Among them, only AKT1 expression was found to be significantly (p = 0.0129) correlated with progression of cancers." (PMID 33092235, 2020). "Here, we also evaluated the functional relationships between miR-3135b and AKT1/mTOR signaling which is active in almost all cancers." (PMID 32601379, 2020). "For instance, antisense oligonucleotides targeting AKT1 have multiple effects on a variety of cancer cell lines, including reducing the ability to grow on soft agar, inducing apoptosis, and increasing sensitivity to various chemotherapeutic agents." (PMID 33354218, 2020). "So the actions of MET on Akt1/2 are essentially due to a loss/reduction of Akt1/2 activity since when the ratio of active Akt1/2 (phosphorylated) to total Akt1/2 levels is calculated we observed a reduction of Akt1/2 activity in cancer cells." (PMID 33108409, 2020). "SIRT1, AKT1, and MTOR oscillate in both cell lines in a circadian manner and are associated with the circadian clock and cancer hallmarks." (PMID 32295075, 2020).
cancer (continued). "Univariate and multivariate logistic regression analysis of theassociation between AKT1 and AR genes inprostate cancer patients and controls." (PMID 32484847, 2020). "There are three Akt isoforms (Akt1, Akt2, Ak3) found in mammalian cells, each with a distinct role in cancer." (PMID 32012648, 2020). "The AKT1 signaling pathway is a useful prognostic marker of many cancers as well as a promising target for therapies." (PMID 33614606, 2020). "The abnormal expressions of NOS2, DUOX2/DUOXA2, ESR1, EGFR, MYC, and AKT1, which are being discussed in this study, have been confirmed to be related to cancer." (PMID 33299870, 2020). "In order to identify new therapeutic targets for AKT1-dependent cancers, it is important to identify the complete catalog of AKT1-dependent substrates." (PMID 33614606, 2020). "In a high fraction of human cancers, constitutively active oncoprotein Akt1 suppresses autophagy in vitro and in vivo." (PMID 32410999, 2020). "RAC-alpha serine/threonine-protein kinase 1 (AKT1) is also known to promote metastasis, but several data reported its ability to inhibit cancer cell invasion." (PMID 32664456, 2020). "The functional role of AKT2 in the physiologically state and in cancer cells has been reported as opposing compared to AKT1." (PMID 32962206, 2020). "We observed MYC and AKT1 mRNA expression was consistent with copy number amplification across cancer types." (PMID 32635458, 2020). "Several studies have proven that quercetin can attenuate cancer cell migration and invasion by suppressing the protein levels of Akt1, which is consistent with the predicted result." (PMID 32964029, 2020). "Our results showed that two well-known drug target genes in cancer therapy, AKT1 and mTOR were oscillating in both CRC cell lines." (PMID 32295075, 2020). "In this study, the synthesis and in silico and in vitro evaluation of a series of quinazoline analogues as potential anticancer agents targeting AKT1 protein is described, as it is hyperactivated in many cancers." (PMID 33080996, 2020). "We further investigated the indirect link between these cancer hallmarks genes and circadian drug targets in our datasets and identified AKT1 and MTOR as potential circadian drug targets for both of our cell lines." (PMID 32295075, 2020). "Again, our data is in a close consistency with the data published recently by Mueck C. with co-authors illustrating that knockdown of Akt1 significantly reduced the amount of Rad51 protein in the nuclear fraction of irradiated non-small ling cancer cells." (PMID 33266502, 2020). "This is in line with our previous data showing that ESRP1 induces, through AKT1 activation, the release of FGFs in cancer cells, hence activating an autocrine signalling loop." (PMID 31963158, 2020). "We also observed upregulated ALDH activity, which is a CSC marker in different cancers including pancreatic, as well as increased autophagy especially for cancer cells adapted to AKT1 and AKT3 silencing." (PMID 32764385, 2020). "In HER2-mutated cancer cells, HER2 associates with STING and recruits AKT1 to phosphorylate TBK1, the downstream signaling target of STING, thereby preventing STING-TBK1 and TBK1-IRF3 interactions." (PMID 32774773, 2020). "Cinobufacin injection plays an important role in the treatment of malignant tumors by regulating the expression of AKT1, VEFG, EGFR, CASP3, and CXCL8." (PMID 32148531, 2020).
cancer (continued). "On the other hand, CAMK2G which is ubiquitously expressed has been shown to support cancers through activating transcription factors such as AKT1, CREB, CDK1/2." (PMID 32483123, 2020). "Clinical data analysis showed that the high expression of CXCR2 was related to the high expression of cyclooxygenase 2 (COX2) and the low expression of P85A, AKT1 or E‐cadherin, and B‐catenin in cancer tissues." (PMID 32253815, 2020). "This review is intended to provide a better understanding of the role of AKT1(E17K) in cancer and to inform the development of AKT1(E17K)-based antitumor strategies." (PMID 33123537, 2020). "Initial reports on the inhibitory effects of Akt1 activation on cancer cell migration and invasion in vitro came from Toker laboratory." (PMID 31360736, 2019). "EP decreased migratory and invasive effects of cancer cells while inhibiting the expression of total AKT1, AKT2, BCL-XL, Cyclin D1 and c-Myc in the tested IBC cells." (PMID 30837881, 2019). "After a decade-long hiatus, there has been a renewed interest on the dual role of Akt in cancer after it was discovered that the deletion of Akt1 gene in Akt2+/− mice potentiate inflammation-induced hepatic cancer." (PMID 31360736, 2019). "These preclinical studies have identified Akt1 as a molecule that promotes tumor growth but inhibits metastasis in cancer." (PMID 31360736, 2019). "Akt1 also regulates cancer and fibroblast cell chemotaxis by lysophosphatidic acid and PDGF 32, 33 and therefore the regulation of tip cell polarization and movement to hypoxic regions by Akt1 plays an essential role in the angiogenic process." (PMID 30984553, 2019). "The PI3K/Akt signaling pathway is an attractive target in anti-cancer therapy, but unexpected combinational deletion of Akt1 and Akt2 in adult hepatocytes results in liver injury that promotes HCC in mice." (PMID 31488102, 2019). "Previous genetic studies in mice demonstrated that AKT1 deletion inhibited cancer development in various mouse models, whereas AKT2 deletion had limited effects on cancer development in mouse models." (PMID 31113871, 2019). "As expected, known cancer proteins BRAF, PIK3CA, KRas, Akt1, IDH1, and NRas showed the highest hotspot mutation scores in the TCGA dataset." (PMID 31345222, 2019). "Our results suggest the overexpression of Akt1 and 2 with respect to migration and expression of Bcl-2, cyclin D1, and survivin proteins, which are important for cancer cell survival and proliferation." (PMID 31252679, 2019). "Bioinformatics analysis revealed that SNPs in six genes (NCOR1, GATA3, CDH1, ATM, AKT1, and PTEN) were significantly associated with the corresponding expression levels and were involved in multiple pathways involved in cancer development." (PMID 30883028, 2019). "Mutations in six genes (NCOR1, GATA3, CDH1, ATM, AKT1, and PTEN) were significantly correlated with the corresponding expression levels, and were enriched and involved in multiple cancer‐related pathways." (PMID 30883028, 2019). "All Akt isoforms are involved in the induction and progression of human cancer, but the Akt1 and Akt2 isoforms play different roles in certain cancers: Akt1 is critical for cancer induction and Akt2 for metastatic dissemination." (PMID 29440989, 2018). "They will be more selective with better structuralfeatures and a potent and specific anti-cancer activity enhancedfor AKT1 and LMTK3." (PMID 31223209, 2018). "AKT1 is widely documented for its activity in cellular metabolism of several human cancers and when phosphorylated, p-Akt1 is described as playing an important role in the redox modulation of cell cycle progression." (PMID 30647870, 2018).
cancer (continued). "AKT1 is one of the key cellular oncogenes and its activation is also thought to drive the early steps of cancer, albeit, in the brain, AKT is pivotal for neuronal survival." (PMID 29556248, 2018). "PI3K, along with downstream effectors such as AKT1 and mammalian target of rapamycin (mTOR), have been regarded as a possible target for cancer therapy." (PMID 29346447, 2018). "In summary, we extended the role of AKT1 specific activity in the maintenance of an epithelial phenotype to a new cancer type." (PMID 29506489, 2018). "Several classes of chemical inhibitors were developed to repress aberrant Akt1 activity in cancer cells." (PMID 30205513, 2018). "PI3K signaling is activated in human cancers by several different mechanisms, including mutations or amplification of genes that encode key components of the PI3K pathway, like PIK3CA and AKT1, or loss of PTEN." (PMID 29682174, 2018). "There is a good correlation between cancer cell toxicity and Akt1 inhibition by ac-LA in the μM range." (PMID 28903409, 2017). "Of 3 members (AKt1, AKt2, and AKt3) of the AKt family, AKt1 and AKt2 are important signaling molecules related to a diabetic phenotype such as IR; at the genomic level, each is amplified in various cancers including breast cancer." (PMID 29023587, 2017). "In summary, we identified novel aspects of the role of Akt1 in the cellular radiation response and provide evidence that the Akt1-E17K mutant naturally occurring in human tumours protects cancer cells from radiation-induced DNA damage." (PMID 28209968, 2017). "In contrast, carriers of the AKT1 rs2494740 T allele had an increased risk of CRC among E+P users, with about 50% of this SNP–cancer association explained by insulin level." (PMID 29023587, 2017). "While oncogenic AKT1 GOF mutations and amplifications have been linked to a variety of cancers, a recent report has found recurrent one-copy losses of AKT1 in DLBCLs." (PMID 28002793, 2017). "Our data provide evidence to differentiate the conflicting activities of AKT1 in cancer invasion and metastasis based on differences in genetic background." (PMID 28765579, 2017). "This AKT1 activation is important for the K8 phosphorylation, reorganization, migration of cancer cells." (PMID 28209923, 2017). "Novel protein interactions with AKT/mTOR pathway members have been commonly reported to efficiently regulate AKT1 kinase activity in cancers." (PMID 28978011, 2017). "It has been reported that miR-302a involves in maintaining stemness of hESCs, suppressing tumor cell proliferation and inducing cancer cell apoptosis by directly targets Rad52 and AKT1." (PMID 29088754, 2017). "In this study, we found that TCRP1 participates in cell transformation and cancer development through activation of PI3K/PDK1/AKT1 signaling." (PMID 28436990, 2017). "It was reported that in several human cancer cell lines, Akt1 localizes in cytoplasm and Akt2 colocalizes with mitochondria, while Akt3 localizes in both nuclear membrane and nucleus." (PMID 28483982, 2017). "Total AKT (Akt1, Akt2 and Akt3) increased during development of various cancers, but in contrast, Akt1 levels were seen to be diminished." (PMID 28659381, 2017). "Akt1 and Akt2 activities have been reported to play roles for G1/S and G2/M transition in cancer and other somatic cells." (PMID 28483982, 2017). "Akt1 is the most prominent and plays a role in many cellular processes which are important for cancer progression." (PMID 27661110, 2016). "In summary, our findings unveiled the novel mechanism of constitutive hyperphosphorylation on AKT1 in cancer cells, mediated by SMYD3-dependent methylation." (PMID 27626683, 2016). "The AKT1 pathway plays a key role in many types of human cancer by regulating cell proliferation, differentiation, angiogenesis and apoptosis." (PMID 27626683, 2016).
cancer (continued). "In conclusion, our data showed that knockdown of ERGIC3 triggers ER stress-induced autophagic cancer cell death and the suppression of Akt1 activation." (PMID 27588471, 2016). "The fact that of the 10 rarely mutated genes, 5 (BCL2L1, CDC42, DDX5, AKT1 and APC) are listed in cancer gene databases indicates such association-based selection is useful." (PMID 27808240, 2016). "Mutations in the highly homologous kinases AKT1, AKT2, or AKT3 occur in approximately 3-5% of cancers." (PMID 26701849, 2016). "It is known that dysregulation of AKT1 activity is one of the critical factors for the development and/or progression of a variety of human cancers." (PMID 27626683, 2016). "AKT1 is a cytosolic serine/threonine kinase that is overexpressed in various types of cancer and has a central role in human tumorigenesis." (PMID 27626683, 2016). "AKT1 is frequently overexpressed and activate in many types of human cancers including cancers of colon, breast, brain, pancreas and prostate as well as lymphomas and leukemias." (PMID 27980566, 2016). "Except for EMT and AKT1 signaling, miR-149 also involves in DNA topoisomerases functioning pathway to inhibit cancer cell growth." (PMID 27825117, 2016). "We knocked down SMYD3 in cancer cells by specific siRNAs and examined phosphorylation status of AKT1." (PMID 27626683, 2016). "Taken together, these results clearly indicate that SMYD3-mediated Lys 14 methylation on AKT1 must be a good target for anti-cancer treatment." (PMID 27626683, 2016). "ATP-competitive inhibitors and allosteric inhibitors have shown promising efficacy in AKT1-mutant cancers in preclinical studies." (PMID 27515171, 2016). "In the present study, we demonstrate that SMYD3 methylates lysine residues in the PH domain of AKT1, and this methylation is essential for AKT1 activation in human cancer cells." (PMID 27626683, 2016). "It has been demonstrated that Slug can be trans-activated through the PI3K/Akt1 signaling pathway in various cancers." (PMID 27036045, 2016). "It is a downstream mediator of phosphatidylinositol 3-kinase which, along with AKT1, is a key mediator of proliferation and survival pathways frequently activated in cancer." (PMID 27515171, 2016). "AKT1 binds directly on Par-4's leucine zipper domain and then phosphorylates Par-4 to maintain the protein in the cytoplasm leading to cancer cells survival and inhibition of Par-4 apoptotic activity." (PMID 27175591, 2016). "In conclusion, we believe in the potential pharmacological impact of selective Akt2 inhibitors to decrease lung tumor growth as well as cell invasion and metastasis even true that Akt1 also play a role in cancer cell invasion." (PMID 26234648, 2015). "Nevertheless, the molecular mechanisms whereby Akt1-E17K promotes cancer in the human remain to be fully understood." (PMID 26486080, 2015). "A second notable finding of our work is the identification of critical targets of constitutive Akt1 signalling that contribute to maintain cancer stem-like properties of NSCLC TICs." (PMID 26486080, 2015). "We explored the contribution of the SNPs in and around AKT1 SNPs to various smoking traits and individual cancer history in the initial 300 subjects, followed by confirmatory analyses in the remaining 699 subjects." (PMID 26137473, 2015). "The high potency and high selectivity of these compounds warrant further clinical investigation in patients with cancer (and other diseases such as PS) targeting not only AKT1-E17K but also the PI3K/AKT pathway activated by PIK3CA mutations." (PMID 26469692, 2015).